METTL3 (methyltransferase 3, N6-adenosine-methyltransferase complex catalytic subunit)
Diseases named in the same sentence as METTL3 in open-access papers (continued):
Sharing a sentence is not in itself a finding about the gene and the disease.
acute myeloid leukemia (continued). "METTL3 mRNA and protein expression in human acute myeloid leukemia (AML) cells are significantly higher than in healthy hematopoietic stem/progenitor cells (HSPCs) or other types of tumor cells." (PMID 30149601, 2018). "For example, inhibiting METTL3 expression reduces the proliferation and survival of leukemia cells, while FTO inhibitors show therapeutic potential for acute myeloid leukemia." (PMID 40724951, 2025). "Recently, some methyltransferase-like (METTL) proteins have been found to play crucial roles in the development of acute myeloid leukemia (AML) through mediating RNA modifications, such as METTL3/14/16 mediated N6-methyladenosine (m6A) and METTL1 mediated N7-methylguanosine (m7G)." (PMID 40382345, 2025). "For example, methyltransferases METTL3 and METTL14 enhance translation efficiency by adding m6A marks to MYC, a process that supports rapid proliferation in acute myeloid leukemia (AML)." (PMID 41446042, 2025). "Down-regulation of METTL3 expression in bone marrow mesenchymal stem cells of acute myeloid leukemia (AML) induces an increase in AKT protein, leading to enhanced mesenchymal stem cell (MSC) adipogenesis, which contributes to chemotherapy resistance of AML cells." (PMID 41194259, 2025). "Illustratively, the aberrant activities of m6A-regulatory enzymes like METTL3 and FTO have emerged as potential therapeutic targets in acute myeloid leukemia." (PMID 40724951, 2025). "Small-molecule inhibitors of METTL3, such as STM2457, have shown promise in mouse models of acute myeloid leukemia (AML) and ALT-positive neuroblastoma, highlighting the translational potential for targeting m6A." (PMID 40558832, 2025). "Several studies have indicated that METTL3, METTL14, and WTAP are highly expressed in patients with acute myeloid leukemia (AML) and function as oncogenes." (PMID 40171845, 2025). "Research has found that STM2457 can inhibit the catalytic activity of METTL3/METTL14, targeting populations of acute myeloid leukaemia (AML) key stem cells with an IC50 = 16.9 nM and it is identified as a specific METTL3 inhibitor." (PMID 39779466, 2025). "However, under pathological conditions of acute myeloid leukemia (AML), a converse function is reported, wherein the levels of METTL3 are elevated compared to those in healthy HSPCs." (PMID 39416774, 2024). "Furthermore, in acute myeloid leukemia (AML), METTL3, operating independently of METTL14, is recruited to chromatin by the CAATT-box binding protein CEBPZ and localizes to the transcription start site to regulate the translation of target genes." (PMID 38444581, 2024). "For example, METTL3 and METTL14 exhibited an oncogenic role in acute myeloid leukemia (AML), in which they were highly expressed and correlated with shorter survival." (PMID 38503745, 2024). "In acute myeloid leukemia, METTL3 and METTL14 exhibit binding to transcription start sites, but the binding sites of METTL3 and METTL14 are almost entirely distinct." (PMID 38965238, 2024). "They found that in acute myeloid leukemia (AML), METTL3 could be localized to the transcription initiation site of target genes in chromatin independently of METTL14 which was essential for m6A modification." (PMID 36830614, 2023). "In acute myeloid leukemia (AML), METTL3 was upregulated in resistant AML cells compared to the counterparts." (PMID 36810281, 2023). "We recently showed that pharmacological inhibition of the catalytic activity of METTL3, using the first-in-class small molecule STM2457, is a novel therapeutic strategy against acute myeloid leukaemia (AML)." (PMID 37464070, 2023). "In acute myeloid leukaemia, YY1 binds to the promoter of METTL3 by liquid-liquid phase separation, leading to elevated METTL3 expression." (PMID 37996892, 2023). "Recently, a novel and selective METTL3 inhibitor, STM2457 has shown therapeutic effect in acute myeloid leukemia." (PMID 35094011, 2022).
acute myeloid leukemia (continued). "Novel inhibitors of METTL3 have been identified and studied in acute myeloid leukemia (AML) cells." (PMID 35574332, 2022). "The m6A methylation enzyme, methyltransferase-like 3 (METTL3), participates in maintaining pluripotency and inhibiting cell differentiation in acute myeloid leukemia by mediating the elevation of m6A." (PMID 35233461, 2022). "Lots of studies have showed that abnormal expression of METTL3 in acute myeloid leukemia (AML), gastric cancer, pancreatic cancer, breast cancer, hepatocellular carcinoma, and non-small cell lung cancer (NSCLC) and is associated with nasopharyngeal carcinoma, and ovarian cancer." (PMID 35287752, 2022). "The recently reported METTL3 inhibitor, STM2457, has been shown to reduce acute myeloid leukaemia cell proliferation." (PMID 36291932, 2022). "In particular, acute myeloid leukemia (AML), one of the most common types of leukemia with diverse genetic and molecular abnormalities in adults, expresses higher levels of METTL3 and METTL14 compared with other cancer types in the analysis of The Cancer Genome Atlas (TCGA) dataset." (PMID 35455436, 2022). "For instance, the m6A writer, METTL3 was found to promote the translation of c-MYC and BCL2 to accelerate leukemia progression by suppressing differentiation and apoptosis in acute myelocytic leukemia." (PMID 35646049, 2022). "The research team identified, for the first time, a small-molecule inhibitor of the m6A methylase METTL3 in the body, STM2457, and confirmed that this inhibitor effectively inhibits the development of acute myeloid leukemia (AML)." (PMID 35945641, 2022). "In addition, the mRNA and protein levels of METTL3 are higher in acute myeloid leukemia (AML) cells than those in healthy HSPCs." (PMID 34103054, 2021). "The downregulation of METTL3 and METTL14 can induce the apoptosis and differentiation of acute myeloid leukemia (AML) cells." (PMID 33952721, 2021). "However, in a study of acute myeloid leukaemia, METTL3 was found to be necessary for the growth of acute myeloid leukaemia cells and down‐regulation of METTL3 could lead to cell cycle arrest, leukaemia cell differentiation, and even unable to induce leukaemia in immunodeficient mice." (PMID 34075693, 2021). "Similar to METTL3, METTL14 was also proved to accelerate the progression of acute myeloid leukemia (AML)." (PMID 34211849, 2021). "For example, high expression of METTL3 and METTL14 has been observed in acute myelocytic leukemia (AML) and found to mediate transformation of malignant myeloid hematopoietic cells." (PMID 32296573, 2020). "METTL3 and METTL14 are highly expressed in acute myeloid leukaemia (AML) cells compared with normal hematopoietic progenitor cells." (PMID 33029866, 2020). "For instance, the METTL3 and METTL14, highly expressed in acute myeloid leukemia (AML), play a critical role in leukemia progression through promoting translation of target mRNAs, including MYB, MYC, BCL2, and PTEN." (PMID 33292652, 2020). "YTHDF2 and METTL3 have previously been reported as tumor suppressors in HCC, and as oncogenes in pancreatic cancer and acute myelocytic leukemia." (PMID 32391046, 2020). "TCGA data-based analysis has identified acute myeloid leukemia, DLBCL, and prostatic cancer as the top three malignancies with the most expression abundances of METTL3 among common tumors." (PMID 33061938, 2020). "Several members (e.g. METTL3, METTL14, FTO, ALKBH5 and YTHDF2) actively participate in human cancers such as acute myeloid leukaemia (AML), glioblastoma, breast cancer and endometrial cancer." (PMID 31438961, 2019). "Two independent previous studies stated that both METTL3 and FTO played an oncogenic role in acute myeloid leukemia through the diverse downstream targets." (PMID 31230592, 2019). "The depletion of m6A methyltransferase METTL3 reduces the translation efficiency of genes with m6A modification, such as c-MYC, BCL2 and PTEN, and promotes cell differentiation in acute myeloid leukemia." (PMID 30212448, 2018).
acute myeloid leukemia (continued). "These inhibitors have demonstrated efficacy in a broad spectrum of acute myeloid leukemias, and mice and human PDX AML models, suggesting their potential effectiveness in CML blast crisis and TKI-resistant cells, where METTL3 knockdown exhibits a robust antiproliferative effect." (PMID 39085650, 2024). "In acute myeloid leukemia, C/EBPZ binds to the transcriptional initiation site of the METTL3 gene and may play an important role in inflammatory response and cell differentiation." (PMID 38523808, 2024). "Interestingly, the mechanism by which METTL3 enhances MYC expression in an m6A-dependent manner to regulate tumor growth also exists in cervical cancer, bladder cancer, acute myeloid leukaemia, and oral squamous carcinoma." (PMID 37996892, 2023). "One prominent example of interfering with RNA modifying enzymes as a therapeutic strategy is the methyltransferase 3 (METTL3, also called N6-adenosine-methyltransferase) inhibitor STM2457, which is under investigation for the treatment of acute myeloid leukemia (AML)." (PMID 37047081, 2023). "Interestingly, it was reported that METTL3 mRNA and protein expression was increased in acute myeloid leukemia (AML) cells compared to healthy hematopoietic stem and progenitor cells, and a higher expression was reported in pediatric ALL ETV6/RUNX1-positive patients when compared to controls." (PMID 36428851, 2022). "In this study, we investigated the expression of methyltransferase-like 3 (METTL3) and 14 (METTL14), components of the RNA m6A methyltransferase complex, in samples from 89 patients with acute myeloid leukemia (AML), and followed the survival of 75 of these patients." (PMID 35154467, 2022). "In addition, some different components that interact with METTL3 have also been found in the cytoplasm of human cancer cell lines, including HeLa cells, breast cancer cells (MDA-MB-231 cells) and acute myeloid leukemia cells." (PMID 34103054, 2021). "For example, the m6A methyltransferases METTL3/14 and WTAP could act as oncogenic factors by promoting the translation of several oncogenes including c-MYC, BCL2, PTEN, and mTOR in acute myeloid leukemia." (PMID 33584787, 2020). "Research discovered that METTL3 may be related to the occurrence and development of acute myeloid leukemia (AML) since that METTL3 has different effects on the proliferation and growth of various AML cell lines in mice and humans, and its down-regulation can promote the differentiation of AML cells." (PMID 32974160, 2020). "Moreover, in acute myeloid leukemia (AML) cells, METTL3 was abundantly expressed and promoted MYC, BCL2, and PTEN translation through m6A modification, which inhibited cell differentiation and fueled leukemia progression." (PMID 30518868, 2018). "By encouraging the translation of these mRNAs, METTL3 activity boosts and augments MYC, BCL2, and PTEN in human acute myeloid leukemia (AML)." (PMID 36551330, 2022). "It was found that METTL3 and METTL14 (writers) served an oncogenic role in acute myeloid leukemia (AML) in an m6A manner by promoting the translation of MYC, MYB, BCL2, SP1, and PTEN." (PMID 36281789, 2022). "METTL3 and METTL14 are upregulated in acute myeloid leukemia (AML) where they have an established oncogenic function and play a relevant role in AML survival." (PMID 34561421, 2021). "Like the dual role of METTL3, it was also reported that METTL14 acts as an oncogene in acute myeloid leukemia (AML) and breast cancer 49,50." (PMID 33456561, 2021). "Methyltransferase-like 3 (METTL3) is the main catalytic subunit of the m6A methyltransferase complex (MTC) and plays an essential role in various disease indications, including acute myeloid leukemia (AML)." (PMID 40599585, 2025).
acute myeloid leukemia (continued). "Despite numerous studies suggesting that RNA m6A transferase core complex including METTL3 and METTL14 play essential roles in both the initiation and maintenance of acute myeloid leukemia (AML), effective pharmacological targeting of these two proteins remains elusive." (PMID 40453361, 2024). "First, although a study reported that the selective first-in-class catalytic inhibitor of METTL3 (i.e., STM2457) can be used in treatment strategies for acute myeloid leukemia, the inhibitor of METTL3 has not yet been identified for the treatment of CRC." (PMID 35012593, 2022). "In addition, METTL3 depletion in HSCs did not affect apoptosis, whereas knocking down of METTL14 induced acute myeloid leukemia (AML) cell apoptosis and promoted myeloid differentiation of normal HSCs via the SPI1–METTL14–MYB/MYC signaling axis." (PMID 35935968, 2022). "The allosteric inhibitor CDIBA, which features an indole core structure, binds non-competitively and reversibly to the METTL3-METTL14 enzyme complex, and compound 43n optimized from CDIBA exhibits significant antiproliferative efficacy against acute myeloid leukemia (AML) cells." (PMID 40823087, 2025).
bladder cancer (168 papers, 2019 to 2025). "For example, a novel statistical analysis found that METTL3 is a tumor suppressor gene and its somatic mutations promote bladder cancer cell growth/proliferation." (PMID 40734692, 2025). "Specifically, tumor necrosis factor-alpha (TNF-α) drives bladder cancer metastasis via METTL3-mediated m6A modification of cytoplasmic Linker associated protein 2 (CLASP2)." (PMID 40986143, 2025). "METTL3 promotes the maturation of pri-miR221/ 222 and was associated with poor prognosis in bladder cancer patients." (PMID 36553003, 2022). "The survival analysis was adopted to explore the association between METTL3 expression and the prognosis of bladder cancer." (PMID 31228940, 2019). "More importantly, we found that METTL3 expression was associated with the histological grade in bladder cancer patients." (PMID 31228940, 2019). "It has been reported that METTL3 can cause the m6A modification of KLF4 mRNAs in bladder cancer." (PMID 38879589, 2024). "The aims of this study were to determine the association between METTL3/YTHDF1 and bladder cancer cell proliferation and cisplatin resistance to explore the downstream target genes of METTL3/YTHDF1 and to explore the therapeutic implications for bladder cancer patients." (PMID 37108067, 2023). "For example, in bladder cancer, METTL3 is significantly overexpressed and is associated with proliferation, invasion, and tumorigenic capacity in in vivo, and METTL3 promotes tumor progression through m6A modification on AFF4 and NF-κB mRNA, which in turn activates MYC transcription." (PMID 36830614, 2023). "Based on a novel statistical model and the following experimental validation, METTL3 was identified as a tumor suppressor gene in bladder cancer and somatic mutations in METTL3 may promote cancer cell growth." (PMID 35399719, 2022). "These abnormalities may be linked to an enzyme called methyltransferase-like 3 (METTL3), which is known to promote chemoresistance in lung and bladder cancers." (PMID 33420414, 2021). "Three other pathways are also associated with METTL3 upregulation in bladder cancer, including the METTL3 -CDCP1 (CUB Domain Containing Protein 1), METTL3-ITGA6(Integrin Subunit Alpha 6), and METTL3/YTHDF2-SETD7/KLF4(SET Domain Containing Lysine Methyltransferase 7/ Kruppel Like Factor 4) m6A axes." (PMID 32765970, 2020). "Furthermore, METTL3 has been implicated in bladder cancer by promoting resistance to CD8+ T cell cytotoxic effects through the upregulation of programmed death ligand 1 (PD-L1) expression, underscoring the importance of m6A methylation in tumor immunity modulation." (PMID 38778403, 2024). "In our previous study, we have demonstrated that METTL3, as a key m6A modified methyltransferase, can positively regulate the methylation level of target genes in bladder cancer." (PMID 40083693, 2025). "METTL3 promotes bladder cancer progression via the AF4/FMR2 family member 4 (AFF4)/NF-κB signaling network." (PMID 40986143, 2025). "In bladder cancer and cardiac hypertrophy models, METTL3 exerts oncogenic and pro-fibrotic effects by facilitating DGCR8-mediated maturation of pri-miR-221/222 in an m6A-dependent manner." (PMID 40547022, 2025). "For instance, in bladder cancer, the maturation of pri-miR221/222 has been found to be expedited by METTL3-mediated m6A modification through its interaction with DGCR8, resulting in decreased PTEN expression." (PMID 40136363, 2025). "For instance, in bladder cancer, the upregulation of METTL3 enhances the methylation of CDCP1 mRNA, promoting its translation and tumor progression." (PMID 40003919, 2025). "In colorectal cancer (CRC) and bladder cancer (BC), METTL3 accelerates the cell cycle of tumor cells by directly promoting the expressions of CCNE1, AF4/FMR2 family member 4 (AFF4), two key regulators of the NF-κB pathway (IKBKB and RELA), and MYC." (PMID 40136363, 2025).